S100P (S100 calcium binding protein P)
Diseases named in the same sentence as S100P in open-access papers (continued):
Sharing a sentence is not in itself a finding about the gene and the disease.
colitis (1 paper, 2018). Inflammation of the colon. "While LYZ has been associated with colitis, and S100P associated with the progression of colitis-associated dysplasia, neither LYZ nor NPSR1 had been shown to be associated with CAC." (PMID 29983891, 2018). "Further, we have extended these findings and confirmed the presence of these signatures at the protein level in CAC organoids and tissues, demonstrating increased expression of LYZ and S100P in both colitis and CAC, and increased expression of NPSR1 in colitic organoids and tissues." (PMID 29983891, 2018). "In some cases, S100P expression correlated with progression of colitis into CAC." (PMID 29983891, 2018). "Previous studies indicating a role of S100P in colitis and CAC were also validated." (PMID 29983891, 2018).
colorectal tumours (1 paper, 2022). "S100P was significantly increased in metastasising colorectal tumours compared to non-metastasising primary tumours." (PMID 35597866, 2022). "Expression of S100P and MACC1 correlated positively in CRC cells and colorectal tumours." (PMID 35597866, 2022).
dental caries (1 paper, 2018). The decay of a tooth, in which it becomes softened, discolored, and/or porous. "As a result of MRM, protein S100 A9, protein S100 P, coronin 1A and alpha-2-macroglobulin were shared in HDC vs NDC and HDC vs LDC with higher expression levels in HDC group, indicating their potential diagnostic values in the childhood dental caries." (PMID 29351798, 2018).
dermatofibromas (1 paper, 2022). "On immunohistochemistry, the dermatofibromas are negative for S100P." (PMID 34514564, 2022).
endometrioid carcinoma (1 paper, 2020). "In the present study, we revealed that S100P is involved in the progression of endometrial cells from precancerous lesions to endometrioid carcinoma." (PMID 32883230, 2020). "Moreover, the observation that S100P signals increased in CH and AH, indicated that S100P is expressed early in endometrial tumorigenesis and might play a positive role in the development and progression of endometrioid carcinoma." (PMID 32883230, 2020).
gallbladder disease (1 paper, 2024). "However, the analysis from this present study indicates that S100P does not aid in gallbladder disease differentiation as the stain showed pan-positivity from NL to IAC tissue." (PMID 39334193, 2024).
influenza (1 paper, 2024). An acute viral infection of the respiratory tract, occurring in isolated cases, in epidemics, or in pandemics; it is caused by serologically different strains of viruses (influenzaviruses) designated A, B, and C, has a 3-day incubation period, and usually lasts for 3 to 10 days. "In contrast, PCOLCE2, TDRD9, MPO, MAOA, RAP1GAP, and S100P expression was higher in the severe influenza group compared to the non-severe influenza group in the training cohort, similar to the findings in the validation cohort." (PMID 38454348, 2024). "The ten common DEGs (PCOLCE2, HLA_DPA1, LOC653061, TDRD9, MPO, HLA_DQA1, MAOA, S100P, RAP1GAP, and CA1) that were obtained by overlapping genes from computing the three algorithms [LASSO regression, SVM-RFE algorithms, and RF are candidate key genes for severe influenza." (PMID 38454348, 2024).
medulloblastoma (1 paper, 2007). A malignant, invasive embryonal neoplasm arising from the cerebellum. "Overexpression of several of the S100 proteins is thought to be involved in tumour progression, such as S100A4, which is upregulated in many cancers including medulloblastoma and promotes angiogenesis and metastasis and S100P which is associated with metastasis in breast and pancreatic cancer." (PMID 17579622, 2007).
myocardial ischemia (1 paper, 2019). A disorder of cardiac function caused by insufficient blood flow to the muscle tissue of the heart. "Myocardial ischemia or necrosis promotes the production of inflammatory factors such as S100B, S100A6, S100P, and RAGE in the infarct area; activates the S100-RAGE axis; and induces the increase of inflammatory cytokines." (PMID 31275446, 2019).
pancreatitis (1 paper, 2021). Inflammation of the pancreas. "Compared with patients with pancreatitis, the content of S100P in the pancreatic juice of PC and IPMN patients was significantly increased." (PMID 34527585, 2021). "Thus, measuring the expression level of S100P in pancreatic juice might help distinguish pancreatitis from tumor disease for early screening and diagnosis of PC." (PMID 34527585, 2021).
paraganglioma (1 paper, 2018). A benign or malignant neoplasm arising from paraganglia located along the sympathetic or parasympathetic nerves. "As expected, in both positive controls (i.e., in human paraganglioma tissue and in snakes’ brains), S100p was diffusely positive." (PMID 30199552, 2018).
periodontal disease (1 paper, 2023). "S100-P, on the other hand, is a calcium-binding protein known to play a role in cell proliferation, survival, and differentiation, which may be involved in the pathogenesis of periodontal disease." (PMID 37834046, 2023).
prostate adenocarcinoma (1 paper, 2021). "In descending order of importance to distinguish from prostate adenocarcinomas, genes for uroplakin II, S100P, GATA3 and thrombomodulin had high discriminant loadings (> 0.3)." (PMID 33762601, 2021).
secondary biliary cirrhosis (1 paper, 2020). Secondary biliary cirrhosis develops due to long-term partial or total obstruction of the large bile ducts outside of the liver. "Two of three patients who died of secondary biliary cirrhosis had BilIN lesions, and the positive expressions of γ-H2AX and S100P were detected in the BilIN lesions of one of the two patients." (PMID 33369464, 2020).
senile osteoporosis (1 paper, 2021). "As blocking of the S100P/RAGE interaction is clinically beneficial for cancer therapy, blocking of S100P function may also be helpful in inhibiting osteoclast differentiation and activity in senile osteoporosis or osteolysis caused by bone metastasis of cancer cells." (PMID 34200172, 2021).
Ulcerative (1 paper, 2015). "Ulcerative CRC, characterized by the downward invasion into the bowel wall and peri-colonic soft tissue, displayed strong to weak S100P expression, indicating that S100P overexpression is not a key determinant in conferring the process of invasion." (PMID 25585623, 2015).
tumor (138 papers, 2005 to 2026). "Thereafter, we detected an elevated expression of several tumor cell‐associated markers, including S100P, KRT17, KRT16, KRT7, and LY6D, as previously reported." (PMID 41164952, 2026). "Elevated S100P expression was significantly associated with poorer OS, while tumor size, N stage, TNM stage, and S100P expression emerged as key prognostic factors." (PMID 41301873, 2025). "Correlation analysis demonstrated a significant association between S100P expression and tumor size in patients with PC." (PMID 41301873, 2025). "Analysis of clinical factors revealed that S100P expression was significantly associated with gender, tumor M stage, and race in LUAD and gender in LIHC." (PMID 40224483, 2025). "S100P plays a multifaceted role in tumor development, and its expression has been associated with poor outcomes in several gastrointestinal cancers." (PMID 41301873, 2025). "Authors have described that S100P encodes a calcium-binding protein expressed in different tumor tissues and functionally involved in the malignant phenomenon, which corroborates the present results." (PMID 39594999, 2024). "Some members of this family, such as S100A4, S100A8/A9, S100P, and S100B, mediate the interaction between tumor and stromal cells, and thus, have been implicated in tumor progression, angiogenesis, and metastasis." (PMID 38499391, 2024). "This interaction between Ezrin and S100P has been implicated in tumor cell migration, where the resulting activation of Ezrin promotes the transendothelial migration of tumor cells." (PMID 37371090, 2023). "Spearman correlation test was used to examine the correlation between S100P expression and immune checkpoint genes, and tumor mutation burden (TMB)." (PMID 37853345, 2023). "S100P expression is linked to cancer cell proliferation and motility and contributes to tumour progression in several solid cancers, including CRC." (PMID 35597866, 2022). "Initially, 93 proteins were found, and up to 30 overexpressed were selected, and CD44, S100A7, and S100P were significantly associated as putative candidates for the early phase of tumor progression." (PMID 36412636, 2022). "There is increasing evidence suggesting that the deregulated expression of S100P associated with the tumor growth, progression and metastasis of various types of human cancer 94, such as breast 95, nasopharyngeal carcinoma 96 and pancreatic cancer." (PMID 36046652, 2022). "S100P overexpression was also associated with increased angiogenesis and metastasis in subcutaneous tumor xenograft models." (PMID 36177001, 2022). "S100P is also linked to the immortalization of breast epithelial cells in vitro, tumor progression and early relapse in patients." (PMID 33042844, 2020). "The association between S100P and cellular processes such as cell survival, proliferation, tumour invasion and angiogenesis have been studied by various researchers." (PMID 33238953, 2020). "In the subset of tumours expressing E-cadherin, patients with loss of S100P displayed poorer disease-free survival when compared to those expressing S100P." (PMID 31767037, 2019). "Specifically, patients with loss of E-cadherin and retaining S100P expression had a median overall survival of 29 months whereas that of patients bearing tumours with loss of both proteins (E-cadloss/S100Ploss) increased to 40 months." (PMID 31767037, 2019). "S100P expression was then detected in tumor cell lines and carcinomas derived from the prostate, breast, colon, pancreas, and other tumor types, and it is associated with immortalized, malignant, hormone-independent, and chemoresistant phenotypes." (PMID 25780527, 2015).
tumor (continued). "We demonstrated that high tumor stage (stage II and III) in HCC, which had vascular invasion and various degrees of intrahepatic spread, was more frequently associated with S100P expression, compared with HCCs of low tumor stage (stage I)." (PMID 23785431, 2013). "We found that ETR (P<0.0001), high tumor stage (P = 0.0256), and S100P expression (P = 0.0044) were independent risk factors for poor survival in HCC patients." (PMID 23785431, 2013). "Similarly, RAB27A and S100P are two genes linked to tumor development that are located within APL-specific enhancers that also harbor multiple PML-RARA binding sites and where enhancer interactions are dependent on the PML-RARA protein." (PMID 41168841, 2025). "Single-cell analyses further demonstrated enriched S100P expression in tumor-associated cells." (PMID 40433361, 2025). "Moreover, Cromolyn interferes with the function of S100P, a protein associated with tumor growth and metastasis, in pancreatic cancer cells." (PMID 38647571, 2024). "This study identifies S100P as a novel molecular determinant of E-cadherin function in GC providing critical information for the management of patients harbouring E-cadherin associated tumours." (PMID 31767037, 2019). "The expression of S100P may identify HCC patients with high tumor stage or ETR that are at increased risk for reduced survival, aiding in the development of improved management strategies." (PMID 23785431, 2013). "Co-expression of TFF1 and S100P has been linked to airway dissemination in NSCLC, indicating their roles in promoting tumor progression." (PMID 40787454, 2025). "Multivariate analysis of variables with p < 0.05 indicated that tumor size (p = 0.022) and S100P expression (p = 0.039) were independent prognostic factors for OS, whereas N stage and TNM stage were not significant." (PMID 41301873, 2025). "Multivariate analysis identified tumor size and S100P expression as independent prognostic indicators." (PMID 41301873, 2025). "S100P is overexpressed in multiple cancers and linked to poor prognosis in LUAD, while S100A10 contributes to membrane repair and drug resistance in tumor progression." (PMID 40433361, 2025). "Intracellularly, S100P can activate Ezrin, thereby promoting the transendothelial migration of tumor cells." (PMID 41301873, 2025). "In the Asian population, upregulated genes such as AKR1B10, UBE2C, and S100P are involved in immune modulation and tumor progression." (PMID 41216224, 2025). "For instance, S100P enhances cancer cell proliferation, cytoskeletal reorganization, and resistance to apoptosis, contributing to tumor progression and poor treatment response." (PMID 41404073, 2025). "This dynamic equilibrium enables PC cells to survive and adapt under varying microenvironmental and physiological conditions by flexibly modulating the relative expression of CTSE and S100P, thereby influencing tumor progression and metastasis." (PMID 41301873, 2025). "Univariate analysis for S100P revealed that tumor size (p = 0.001), N stage (p = 0.012), TNM stage (p = 0.031), and S100P expression (p = 0.024) were significantly associated with OS." (PMID 41301873, 2025). "MZT2A is a key gene involved in mitotic spindle formation and promotes cell proliferation, while S100A6 and S100P are well-known marker genes for tumor cells." (PMID 39883515, 2024). "This includes the activation of tumor promoter genes (such as MAGE and S100P) and the silencing of tumor suppressor genes (such as VHL and MLH1) in a variety of cancers." (PMID 38510251, 2024). "On immunohistochemistry, the tumor cells were positive for S100P and SOX-10 and focally positive for HMB-45 and Melan A. Tumor cells were negative for CK, EMA, SMA, TTF1, PAX8, GATA3 and SALL4." (PMID 38509523, 2024). "The authors used scRNA-seq on CCA cells from fourteen patients with iCCA and non-tumor liver tissues to identify S100P and SPP1 as markers for various types of iCCA." (PMID 39410050, 2024).
tumor (continued). "Tumor samples with high expression of RBMS1 exhibited increased S100P levels and the level of S100P was positively correlated to that of RBMS1 in clinical samples (R = 0.5587, P < 0.0378)." (PMID 38342601, 2024). "Given the impact of tumor-infiltrating immune cells on cancer progression and therapy, further investigation into the role of S100P in the tumor microenvironment and its potential for immunotherapy is imperative." (PMID 37853345, 2023). "The extent of upregulation is dependent on the degree of differentiation of tumor cells, with the most poorly differentiated, from more advanced disease, having the highest level of S100P expression." (PMID 36985425, 2023). "Further analysis of the GSE155698 dataset, which included 41,378 cells from 17 tumor samples, revealed that high expression of S100P was also predominantly observed in malignant cells." (PMID 37853345, 2023). "By interacting with ezrin/radixin/moesin, S100P can promote trans-endothelial migration of tumor cells, thereby favoring metastasis." (PMID 37627239, 2023). "A study conducted on S100P showed that it was present at very high levels in the serum and bile of patients with CCa, and the S100P mRNA was highly expressed in CCa tumor tissues." (PMID 37927641, 2023). "S100P is a member of S100 protein family and functions as a regulator of diverse cellular processes, especially tumor cell lines and tissues." (PMID 37469437, 2023). "A statistically significant correlation was found between S100A11 and S100P (R = 0.73), both in cell lines and in the tumor array (R = 0.62)." (PMID 37627239, 2023). "In contrast to previous findings, however, the present study found that level of expression of S100P mRNA was significantly higher in tumor samples than in adjacent normal tissue." (PMID 36177001, 2022). "The transcription factor CREB3L1 is identified to regulate the S100P expression and promote tumor cell invasion." (PMID 35347134, 2022). "In this subgroup, the risk of a patient to develop metachronous metastases is almost 70% increased when the tumour expresses high S100P levels, emphasising the value of S100P as a prognostic biomarker." (PMID 35597866, 2022). "Eleven DEGs were observed between tumor and adjacent normal tissue including S100P, PHGR1 and S100A6." (PMID 36253784, 2022). "The correlated expression of MACC1 and S100P was validated in publicly available microarray datasets of CRC tumours from the Gene Expression Omnibus repository." (PMID 35597866, 2022). "Our results are also in line with the reported contribution of S100P to tumour progression and metastasis, as its ectopic expression in SW480 cells induces anchorage-dependent and -independent proliferation, cell migration and invasion." (PMID 35597866, 2022). "Here, by performing single-cell RNA sequencing on 144,878 cells from 14 pairs of iCCA tumors and non-tumor liver tissues, we find that S100P and SPP1 are two markers for iCCA perihilar large duct type (iCCAphl) and peripheral small duct type (iCCApps)." (PMID 35347134, 2022). "Compared to iCCApps, iCCAphl comprises mucin-producing columnar tumor cells and has high invasiveness and high expression of S100P, which is more similar to ECC8." (PMID 35347134, 2022). "According to the reports, in addition to promoting tumor migration, invasion, and metastasis, S100P also enhances cell proliferation by up-regulating cyclin D1 and CDK225 and confers chemoresistance by binding and inactivating p5326,27." (PMID 35013450, 2022). "We confirmed that the seven S100P- iCCAs showed high expression of SPP1 both at the cellular (87.17% of S100P- iCCAs’ tumor cells) and tissue level." (PMID 35347134, 2022). "We observed moderately increased tumour growth in the group with transplanted SW480/luc/S100P cells, compared to transplanted SW480/luc/vector cells." (PMID 35597866, 2022).